THRSP (thyroid hormone responsive)
Diseases named in the same sentence as THRSP in open-access papers:
THRSP is named in the same sentence as 37 diseases in open-access papers, as found by Europe PMC text mining. Sharing a sentence is not in itself a finding about the gene and the disease. The quoted sentences say what the papers report.
breast carcinoma (14 papers, 2010 to 2024). "In humans, amplification of the THRSP locus is associated with lipogenic breast cancer; and, as such, THRSP serves as a marker of aggressive breast cancer and a potential target of anti-cancer drugs." (PMID 23947536, 2013). "The thyroid hormone-sensitive protein (THRSP; Spot14; S14) is a nuclear protein that is abundantly expressed in lipogenic tissues such as in the liver, mammary gland, AT and lipogenic breast cancers." (PMID 39036793, 2024). "To extend these findings, we investigated TSPAN8 and THRSP expression among the germline BRCA2-mutant tumours in the TCGA breast cancer dataset." (PMID 37626143, 2023). "THRSP was strongly expressed in most lipogenic breast cancers, and high expression of THRSP predicted a high recurrence rate of primary invasive breast cancers." (PMID 35196258, 2022). "THRSP mediated lipogenic effects of progestin, and THRSP knockdown disrupted lipid synthesis and induced apoptosis of breast cancer cells." (PMID 35196258, 2022). "The thyroid hormone sensitive protein (THRSP; Spot14; S14) is a nuclear protein, which is abundantly expressed in lipogenic tissues such as in liver, mammary gland, and adipose tissue (AT) and lipogenic breast cancers." (PMID 35715726, 2022). "Moreover, THRSP can also mediate progesterone-induced adipogenesis and promote the growth of breast cancer cells 9-11." (PMID 34093825, 2021). "The THRSP gene also modulates tumorigenesis in human breast cancer." (PMID 20149241, 2010). "Moreover, THRSP inhibited growth and induced cell death of human breast cancer cells." (PMID 28273073, 2017). "In contrast with prior findings in breast cancer, we observed that THRSP expression was frequently reduced in HCC and that down-regulation of THRSP was positively correlated with recurrence, larger tumor size, and more aggressive phenotype." (PMID 34093825, 2021). "Up-regulated expression of COL10A1, MMP11, CST1, GJB2, MMP1, MMP13, and CEACAM6; down-regulated expression of ADH1B, CIDEC, THRSP, GPD1, TIMP4, FABP4, and SCARA5 genes was common in breast cancers of the two populations." (PMID 31292488, 2019). "GISTIC identifies a peak encompassing four genes (THRSP, NDUFC2, ALG8 and KCTD21), amplification of which have been shown in breast cancer to correlate with over-expression and poor survival." (PMID 20844748, 2010).
Obesity (6 papers, 2019 to 2023). Accumulation of substantial excess body fat. "In mice, THRSP acts in the regulation of diet-induced obesity, while THRSP-knockout leads to deficiencies in de novo lipogenesis in the lactating mammary gland." (PMID 35003205, 2021). "Thyroid hormone responsive protein (THRSP) is involved in lipogenic processes and is associated with obesity and differential intramuscular fat in cattle." (PMID 31057604, 2019). "Of interest, a previous study has shown that THRSP expression is decreased in obesity." (PMID 35715726, 2022). "Fluctuations in THRSP expression might represent a physiologic response to nutritional and hormonal stimuli, which are known to be disturbed in obesity and metabolic disease." (PMID 35715726, 2022).
hepatocellular carcinoma (4 papers, 2021 to 2022). A malignant tumor that arises from hepatocytes. "In hepatocellular carcinoma, downregulation of THRSP decreased epithelial markers and increased mesenchymal markers, hence facilitating epithelial to mesenchymal transformation (EMT) which is a critical process in tumor migration and invasion." (PMID 35945747, 2022). "Mechanistically, THRSP inhibited hepatocellular carcinoma progression by inhibiting the ERK/ZEB1 pathway induced EMT process." (PMID 34093825, 2021). "This aligns with previous research demonstrating that T3 inhibits various long non-coding RNAs in hepatocellular cancer—this inhibition could thus be mediated via THRSP." (PMID 35715726, 2022).
hypothyroidism (4 papers, 2012 to 2024). Abnormally low levels of thyroid hormone. "Physiological characterization revealed low striatal T3 levels in the THRSP OE mice due to reduced striatal T3-specific monocarboxylate transporter 8 (MCT8), indicating brain-specific hypothyroidism in this transgenic mouse strain." (PMID 34545202, 2021).
liver cancer (4 papers, 2017 to 2022). An epithelial or non-epithelial malignant neoplasm that arises from the liver. "In this study, data from public databases and biological experiments were combined to investigate the mechanism by which THRSP influences liver cancer." (PMID 34093825, 2021). "According to TCGA database, mRNA expression of THRSP was down-regulated in 374 patients with liver cancer, compared with 50 normal samples (P<0.01)." (PMID 34093825, 2021). "Moreover, downregulation of THRSP was validated by qPCR and WB analyses in liver cancer cell lines relative to normal liver cells." (PMID 34093825, 2021). "We also observed reduced tumor formation upon enforced expression of THRSP, which encodes an acidic protein that responds robustly to thyroid hormone stimulus that has not been previously linked to liver cancer." (PMID 28273073, 2017). "Although THRSP was not expressed in either of the human liver cancer cell lines we tested, enforced expression of THRSP significantly reduced tumor burden of Huh7 cells in vivo." (PMID 28273073, 2017). "We also demonstrated that two additional genes without a prior known role in liver cancer, CADM4 and THRSP, have strong anti-tumorigenic activity in this tumor type." (PMID 28273073, 2017). "Our data also suggest that DKK4 and THRSP may not be targets of SRC-2 in HepG2 cells, and thus may be dysregulated in liver cancer cells through additional SRC-2-independent mechanisms." (PMID 28273073, 2017).
Insulin resistance (2 papers, 2013 to 2022). Increased resistance towards insulin, that is, diminished effectiveness of insulin in reducing blood glucose levels. "Moreover, clinical features associated with insulin resistance, such as the waist-to-hip ratio, SAT volume, serum insulin and C-peptide concentrations, and fasting plasma glucose concentrations, correlated inversely with THRSP expression." (PMID 35715726, 2022).
memory impairment (2 papers, 2021 to 2023). "Overall, we observed that THRSP overexpression induces striatal T3 deficiency, inattention, memory impairment, and theta wave alterations in mice." (PMID 34545202, 2021). "Collectively, these findings suggested a relationship between the inherent impairment of Wnt signaling, reduced NSC activity, inattention, and memory impairment in THRSP OE mice, which were improved by a combination of EE and treadmill exercises." (PMID 36646879, 2023). "We have established the potential effects of THRSP gene overexpression on striatal T3, leading to inattention and memory impairment in mice." (PMID 34545202, 2021). "Because the THRSP gene is innately responsive to TH, we evaluated its function in mice and determined its implications for the inattention and memory impairment observed in THRSP OE mice." (PMID 34545202, 2021). "Here we found that reduction in striatal T3 levels influences the inattention, memory impairment, and theta waves reduction in THRSP OE mice, indicating the role of TH in ADHD pathogenesis, particularly in the predominantly inattentive subtype of ADHD (ADHD-PI)." (PMID 34545202, 2021). "We speculate that the functional deletion and overexpression of THRSP in mice influence the production of NSPCs, which are highly responsive to TH, which may be involved in the inattention and memory impairments or the lack thereof in these transgenic mice." (PMID 34545202, 2021). "We now confirm that THRSP overexpression in male mice reproduces behavioral features of ADHD, including sustained inattention and memory impairment, accompanied by excessive theta waves that were found normal in both the THRSP-knockout and hetero groups." (PMID 34545202, 2021). "The exact mechanism by which the overexpression, but not the knockout of THRSP gene, induces inattention and memory impairment is still unclear." (PMID 34545202, 2021).
psoriasis (2 papers, 2007 to 2023). An autoimmune condition characterized by red, well-delineated plaques with silvery scales that are usually on the extensor surfaces and scalp. "Moreover, the lipid metabolism genes THRSP and GAL, which are expressed by keratinocytes and in eccrine sweat glands, have also been reported to be downregulated in uninvolved psoriasis skin." (PMID 37131254, 2023).
anemia (1 paper, 2016). A reduction in the number of red blood cells, the amount of hemoglobin, and/or the volume of packed red blood cells. "It is probable, therefore, that decrease in the levels of THRSP, FASN, and FABP4 expression in the LowFe animals is an adaptation to a smaller quantity of iron, since iron deficiency, with or without anemia, harms thyroid metabolism." (PMID 27532424, 2016).
Anxiety (1 paper, 2021). Intense feelings of nervousness, tension, or panic often arise in response to interpersonal stresses. "Also, the anxiety observed in the elevated-plus maze (EPM) and motor balance impairment as assessed by performance in the rotarod tests were absent in these strains, which further confirms that THRSP is an inattention-specific genetic marker." (PMID 34545202, 2021).
atopic dermatitis (1 paper, 2018). "Some of lipid metabolic genes discovered in our analysis were also reported as declined genes in patients with psoriatic (ACSBG1, ALOX15B, ELOVL3, FADS1, FADS2, and THRSP) or atopic dermatitis (CYP4F8, ELOVL3, FADS1, FADS2, FAR2, and HAO2)." (PMID 30021930, 2018).
depression (1 paper, 2020). "Finally, the physiological importance of the reduced level of the gliotransmitter lactate and the increased expression of cytotoxic THRSP in the hippocampus in the model of depression used in this study should be determined in further studies." (PMID 33343282, 2020).
fibrosis (1 paper, 2014). the formation of excess fibrous connective tissue in an organ or tissue in a reparative or reactive process. "THRSP mRNA levels in patients with advanced NAFLD fibrosis were significantly lower than in patients with mild NAFLD fibrosis, reflecting fibrosis-related changes in D1 and D3 and worsened intrahepatic hypothyroidism with advancing fibrosis." (PMID 25121996, 2014).
Hyperinsulinemia (1 paper, 2022). An increased concentration of insulin in the blood. "To this end, we studied THRSP expression in AT biopsies of 36 individuals, obtained during euglycemic hyperinsulinemia." (PMID 35715726, 2022). "We found insulin to increase THRSP mRNA expression 5- and 8-fold after 180 and 360 min of in vivo euglycemic hyperinsulinemia." (PMID 35715726, 2022). "We studied the expression of THRSP before and during euglycemic hyperinsulinemia in vivo and found that insulin significantly induced THRSP expression, which was enhanced in subjects with high insulin sensitivity." (PMID 35715726, 2022). "Adipose tissue biopsies were obtained at baseline and after 180 and 360 min of euglycemic hyperinsulinemia for measurement of THRSP mRNA concentrations." (PMID 35715726, 2022). "A publicly available microarray dataset (GSE26637) from our previous study was used to identify differentially expressed genes in AT during euglycemic hyperinsulinemia, and the altered gene profile was then compared with transcriptomic changes in the THRSP-silenced SGBS adipocytes." (PMID 35715726, 2022).
lymph node metastasis (1 paper, 2022). "Then, the factors influencing THRSP mRNA expression were explored, and the function of THRSP in predicting the lymph node metastasis (LNM) stage was determined." (PMID 35945747, 2022).
lysosomal storage disease (1 paper, 2022). A metabolic disorder caused by mutations in proteins critical for lysosomal function, including lysosomal enzymes, lysosomal integral membrane proteins, and proteins involved in the post-translational modification and trafficking of lysosomal proteins. "Therefore, it might be of interest to study a possible role of THRSP in lysosomal storage diseases." (PMID 35715726, 2022).
metabolism (1 paper, 2024). "By interfering with the expression of the THRSP gene, the occurrence of abnormal lipid metabolism diseases associated with ER stress can be ameliorated." (PMID 39766829, 2024).
non-alcoholic fatty liver disease (1 paper, 2025). "In the liver, THRSP expression is rapidly induced by stimuli promoting long-chain fatty acid synthesis, such as THs, glucose, and insulin, and it plays a pivotal role in the pathogenesis of non-alcoholic fatty liver disease." (PMID 40055330, 2025).
Simpson-Golabi-Behmel syndrome (1 paper, 2022). Simpson-Golabi-Behmel syndrome is a rare X-linked multiple congenital anomalies syndrome, characterized by pre- and postnatal overgrowth, distinctive craniofacial features, variable congenital malformations, organomegaly and an increased tumor risk. "We characterized the insulin regulation of THRSP in vivo in human adipose tissue biopsies and in vitro in Simpson-Golabi-Behmel syndrome (SGBS) adipocytes." (PMID 35715726, 2022).
thyroid cancer (1 paper, 2022). "Since the LNM stage is an essential predictor of thyroid cancer prognosis and we have demonstrated that it was significantly related to THRSP mRNA expression, we next investigated its role in predicting the LNM stage." (PMID 35945747, 2022). "GO and KEGG analyses of THRSP and its co-expressed genes in thyroid carcinoma." (PMID 35945747, 2022). "The study aimed to evaluate the clinical significance of thyroid hormone-responsive (THRSP) and explore its relevant pathways in thyroid carcinoma (THCA)." (PMID 35945747, 2022).
tumor (10 papers, 2015 to 2025). "Indeed, the high expression of THRSP in primary invasive breast cancer was proved to predict the time to tumor recurrence, with greater expression associated with less recurrence-free survival." (PMID 34093825, 2021). "Tumor volume and weight were significantly smaller in the THRSP-OE group compared to the control group." (PMID 40055330, 2025). "Four genes (UGT2B17, SST, CRYGB, and THRSP) were downregulated in tumor samples, whereas eighty genes were increased." (PMID 36785673, 2023). "Another study reported that over-expression of THRSP increased medium-chain fatty acids synthesis and cell proliferation, but reduced tumor metastasis." (PMID 35196258, 2022). "To further demonstrate that THRSP suppressed tumor cell growth, we measured molecular markers of cell proliferation and invasion in the subcutaneous xenograft tumors." (PMID 34093825, 2021). "The observed upregulation of DPEP3 and THRSP in high-grade tumors aligns with their established roles in tumor progression and metabolic reprogramming, while the downregulation of differentiation markers like KRT33A suggests a loss of epithelial characteristics in aggressive disease." (PMID 41155123, 2025). "Over expression of this protein was seen to reduce the tumour latency period in mice and increase proliferation; however, this same study showed an overwhelming reduction in lung metastasis in these same mice compared to controls or THRSP knockout mice." (PMID 35697697, 2022). "In addition, THRSP expression was negatively correlated with most of the immune cells, and it might play an important role in the tumor microenvironment of HCC." (PMID 35196258, 2022). "The results revealed that THRSP may be related to tumor cell growth, and proliferation." (PMID 35945747, 2022). "Knockdown of THRSP led to increased cell growth, migration, and invasion of HCC cells, and THRSP overexpression exerted an anti-tumor effect in vivo and in vitro." (PMID 34093825, 2021). "Notably, DPEP3 (dipeptidase 3), THRSP (thyroid hormone responsive), and SLC5A8 (solute carrier family 5 member 8) were significantly upregulated in high-grade tumors, suggesting roles in tumor progression and metabolic reprogramming." (PMID 41155123, 2025). "In contrast, overexpression of either DKK4 or THRSP alone significantly impacted rates of cell proliferation but not tumor burden." (PMID 28273073, 2017). "The data showed an increase in TSPAN8 expression, but not THRSP expression, in BRCA2-mutant tumours compared with wild-type tumours." (PMID 37626143, 2023).
cancer (8 papers, 2013 to 2025). A tumor composed of atypical neoplastic, often pleomorphic cells that invade other tissues. "Pan-cancer analysis showed that abnormal gene expression of THRSP was observed in 14 cancer types including THCA (all P < .01)." (PMID 35945747, 2022). "Wilcox test was used to compare the difference in THRSP expression or methylation in groups divided by age, family history of cancer, gender, grade, Ishak fibrosis score and race." (PMID 35196258, 2022). "As a small nuclear protein, THRSP has been reported to play an important role in various cancers." (PMID 35945747, 2022). "The observation that THRSP inhibits glycolysis and HCC progression and serves as a prognostic marker for patient survival further underscores its potential as a therapeutic target for cancer treatment and glucose metabolism regulation in HCC." (PMID 40055330, 2025). "However, both TSPAN8 and THRSP expression were lower in BRCA2-mutant and non-BRCA2-related cancers when compared to normal tissue." (PMID 37626143, 2023). "Thyroid hormone responsive (THRSP) gene is primarily known for regulating responses to thyroid hormones, but its expression has been correlated with differential outcomes in some cancers." (PMID 34093825, 2021). "To verify the clinical significance of THRSP in HCC, we first determined the expression of THRSP in both cancer tissues and paired adjacent non-cancerous tissues using qRT-PCR and western blot (WB)." (PMID 34093825, 2021).
metabolic disease (2 papers, 2022 to 2024). A congenital disorder (due to inherited enzyme abnormality) or acquired (due to failure of a metabolically important organ) disorder resulting from an abnormal metabolic process. "Thus, THRSP, the thyroid hormone-responsive protein, is closely associated with metabolic disorders resulting from lipid metabolism." (PMID 39766829, 2024). "Therefore, studying the function of THRSP in lipid metabolism is particularly important in ameliorating lipid-related metabolic diseases." (PMID 39766829, 2024).
THRSP also shares sentences with these, for which no sentence is quoted: invasive breast carcinoma (2 papers); alcoholic liver diseases (1); atherosclerosis (1); cholestasis (1); endocrine system disorder (1); hyperthyroidism (1); hyperthyroxinemia (1); intrauterine growth restriction (1); iron deficiency (1); kidney cancer (1); liver neoplasm (1); metabolic syndrome (1); neurological disorders (1); steatosis (1).